LPGAT1 (lysophosphatidylglycerol acyltransferase 1)
Description:
Lysophospholipid acyltransferase involved in fatty acyl chain remodeling of glycerophospholipids in the endoplasmic reticulum membrane (By similarity). Selectively catalyzes the transfer and esterification of saturated long-chain fatty acids from acyl-CoA to the sn-1 position of 1-lyso-2-acyl phosphatidylethanolamines (1-lyso-PE, LPE), with a preference for stearoyl CoA over palmitoyl CoA as acyl donor. Acts in concert with an unknown phospholipase A1 to convert palmitate phosphatidylethanolamine (PE) species into stearate ones. Provides substrates to the PE methylation pathway, controlling stearate/palmitate composition of PE and phosphatidylcholine (PC) species with an overall impact on de novo hepatic lipid synthesis, body fat content and life span (By similarity). Can acylate lysophosphatidylglycerols (LPG) using various saturated fatty acyl-CoAs as acyl donors. Can also acylate monoacylglycerols with a preference for 2-monoacylglycerols over 1-monoacylglycerols (By similarity). Has no activity toward lysophosphatidic acids (LPA) (By similarity).
Synonyms: LPLAT7; FAM34A; KIAA0205; FAM34A1; NET8
Tractability: Antibody: UniProt predicts a signal peptide or a membrane-spanning region. PROTAC: ubiquitination databases record sites on it; its protein half-life has been measured.
Gene: Protein-coding gene on chromosome 1 (211,743,457 to 211,833,674, reverse strand). Ensembl gene ENSG00000123684.
Subcellular location: Endoplasmic reticulum membrane
Pathways (Reactome):
Metabolism: Acyl chain remodelling of PG
Gene Ontology:
Molecular function: 2-acylglycerophosphocholine O-acyltransferase activity; lysophospholipid acyltransferase activity; 1-acylglycerol-3-phosphate O-acyltransferase activity; 2-acylglycerol O-acyltransferase activity; 2-acylglycerol-3-phosphate O-acyltransferase activity; lysophosphatidylethanolamine acyltransferase activity; 1-acylglycerophosphoserine O-acyltransferase activity; acyltransferase activity
Biological process: positive regulation of fatty acid biosynthetic process; phosphatidylethanolamine acyl-chain remodeling; phosphatidylglycerol acyl-chain remodeling; phosphatidylinositol acyl-chain remodeling; triglyceride biosynthetic process; glycerophospholipid metabolic process
Cellular component: cytoplasm; endoplasmic reticulum membrane; membrane; endoplasmic reticulum
Genetic constraint (gnomAD): Loss-of-function variants: 4 observed, 31.64 expected, observed/expected ratio (o/e) 0.13, 90% interval 0.061 to 0.29. The upper end of that interval is the gene's LOEUF score, 0.29, which puts it in group 1 of 6, group 1 being the genes least tolerant of losing a copy. Missense variants: 216 observed, 340.32 expected, observed/expected ratio (o/e) 0.63, 90% interval 0.57 to 0.71. Synonymous variants: 108 observed, 118.01 expected, observed/expected ratio (o/e) 0.92, 90% interval 0.78 to 1.07.
Homologues: Orthologues: chimpanzee LPGAT1 (99% identical), macaque LPGAT1 (97% identical), rabbit LPGAT1 (92% identical), pig LPGAT1 (91% identical), dog LPGAT1 (90% identical), mouse Lpgat1 (90% identical), rat Lpgat1 (89% identical), guinea pig LPGAT1 (88% identical), tropical clawed frog lpgat1 (75% identical), zebrafish lpgat1 (69% identical), rat Lpgat1l1 (61% identical), Caenorhabditis elegans acl-14 (38% identical), and 2 more. Paralogues in human: LCLAT1 (21% identical), AGPAT3 (21% identical), AGPAT5 (20% identical), AGPAT4 (19% identical).
Diseases named in the same sentence as LPGAT1 in open-access papers:
LPGAT1 is named in the same sentence as 12 diseases in open-access papers, as found by Europe PMC text mining. Sharing a sentence is not in itself a finding about the gene and the disease. The quoted sentences say what the papers report.
Obesity (6 papers, 2013 to 2024). Accumulation of substantial excess body fat. "It is associated with obesity, as demonstrated by studies on LPGAT1 gene polymorphisms in Native Americans and LPGAT1 gene knockout mice fed a high-fat diet." (PMID 38893234, 2024). "In conclusion, we identified several variants in the LPGAT1 region that are nominally but reproducibly associated with obesity in Pima Indians and other Native Americans." (PMID 23505186, 2013). "The reported association of LPGAT1 with obesity may be related to the MGAT activity of this enzyme." (PMID 38893234, 2024). "The Lpgat1 KO mice were reported to be resistant to obesity, which the authors attributed to abnormal mitochondrial function." (PMID 35508627, 2022). "Lysophosphatidylglycerol acyltransferase 1 is regulated by the same micro-RNA that controls the microsomal TG transfer protein and variants in the LPGAT1 gene region are associated with obesity in Pima Indians." (PMID 35131264, 2022). "Based on the associations from our GWAS with BMI and the potential role of LPGAT1 in lipid metabolism and body weight regulation, LPGAT1 was analyzed as a candidate gene for obesity in the Pima Indians of Arizona." (PMID 23505186, 2013). "Loss of whole-body LPGAT1 protects mice from diet-induced obesity but leads to hepatopathy, insulin resistance, and nonalcoholic fatty liver diseases due to oxidative stress, mitochondrial DNA depletion, and mitochondrial dysfunction." (PMID 37217003, 2023). "The Lpgat1–/– mice developed diet-induced obesity and hepatopathy phenotypes." (PMID 34458256, 2021). "A GWAS for BMI in Pima Indians led us to analyze LPGAT1 as a candidate gene for human obesity." (PMID 23505186, 2013). "Therefore LPGAT1 was analyzed as a candidate gene for obesity in Pima Indians." (PMID 23505186, 2013). "Additionally, LPGAT1 is involved in TAG synthesis through its MGAT activity, particularly crucial in the liver, where its expression is increased in obesity." (PMID 38893234, 2024).
hyperlipidaemia (2 papers, 2019 to 2020). "miR-30c was also suggested to participate in improvement of atherosclerosis and hyperlipidemia via decreasing lipid biosynthesis and secretion of lipoproteins by downregulating lysophosphatidylglycerol acyltransferase 1 (LPGAT1) and microsomal triglyceride transfer protein (MTP)." (PMID 32962281, 2020).
demyelinating disease (1 paper, 2022). A broad group of disorders that affect the myelin sheaths that cover the neurons. "However, changes in LPGAT1 and LIPC, which act only on LPC 18:1 but not LPC 18:0, alone can account for the observed deficiency or absence of LPC 18:1, thus suggesting the importance of lipid metabolism in demyelinating disease pathology." (PMID 35027445, 2022).
Hepatic steatosis (1 paper, 2015). Steatosis is a term used to denote lipid accumulation within hepatocytes. "Unlike synthetic MTP inhibitors, miR-30c did not cause hepatic steatosis, likely due to the simultaneous downregulation of genes involved in de novo lipid synthesis, such as lysophosphatidylglycerol acyltransferase 1 (LPGAT1)." (PMID 26226008, 2015).
infertile (1 paper, 2022). "Interestingly, changes in phospholipid molecular species similar to the ones we detected in Lpgat1 mutant zebrafish were detected in seminal plasma from infertile human males and the changes were reported to be correlated with sperm motility." (PMID 35508627, 2022).
lung adenocarcinoma (1 paper, 2024). A carcinoma that arises from the lung and is characterized by the presence of malignant glandular epithelial cells. "The LPGAT1 gene is part of the five-gene metabolic signatures associated with poor prognosis in patients with lung adenocarcinoma." (PMID 38893234, 2024). "In cancer, LPGAT1 expression is increased in lung adenocarcinoma tumors, correlating with a worse prognosis for patients with this cancer." (PMID 38893234, 2024). "Studies on lung adenocarcinoma cancer cells with reduced LPGAT1 expression demonstrate its role in tumor cell proliferation, explaining the correlation with prognosis in lung adenocarcinoma patients." (PMID 38893234, 2024).
tumor (3 papers, 2020 to 2026). "Previous studies showed that LPGAT1 gene expression is upregulated in tumor tissue compared to normal tissue 44–46." (PMID 40385396, 2025). "Significant alteration of amplification in LPGAT1 was observed, and different protein expression levels were also confirmed between the tumor tissue and control." (PMID 32684932, 2020). "Previous researches revealed that LPGAT1 was differentially expressed between normal and tumor tissue and might be potential targets for crucial microRNAs in LUAD." (PMID 32684932, 2020).
LPGAT1 also shares sentences with these, for which no sentence is quoted: cancer (2 papers); hepatopathy (2); nonalcoholic fatty liver disease (2); atherosclerosis (1); Insulin resistance (1).